PARG (poly(ADP-ribose) glycohydrolase)
Diseases named in the same sentence as PARG in open-access papers (continued):
Sharing a sentence is not in itself a finding about the gene and the disease.
cancer (continued). "Other cancer progression-related genes expressed differently under PARG overexpression in PNX0010 cells." (PMID 34638458, 2021). "Overall, these data confirm that in addition to sensitizing cells to PARG inhibition, loss of ARH3 confers PARPi resistance in different types of cells, including BRCA1/2-deficient cancers." (PMID 34019811, 2021). "ARH3 deficiency is therefore a potential novel PARP1 inhibitor resistance mechanism, similar to what has been described for loss of PARG, which causes PARP inhibitor resistance in cancer cells due to stabilization of the PARylation signal." (PMID 34869334, 2021). "Hypomorphic Parg−/− ES cells and particular human cancer cells with PARG knocked down also showed increased sensitivity to DNA-damaging agents, such as alkylating agents and γ-irradiation." (PMID 32344695, 2020). "The relative low abundance of PARG in normal cells, compared to tumors with aberrant PARG overexpression, makes it an attractive target in cancer therapeutics for tumor-selective drug response." (PMID 32295316, 2020). "Currently, specific inhibitors against BER proteins such as Polβ, PNKP, FEN1, Ligase IIIα, and PARP1/PARG have been developed either to sensitize several cancers or to form synthetic lethal partnerships with common cancer mutations." (PMID 33553154, 2020). "Perturbation of the PARP-1/PARG balance by the over-expression of PARG has been also shown to alter the genome methylation pattern to that of cancer cell types." (PMID 32344695, 2020). "PARP and PARG inhibitors exploit and exacerbate these vulnerabilities of cancer cells by destabilizing replication forks and inducing DNA damage." (PMID 32029455, 2020). "It will be interesting to see if PARG inhibitors can recapitulate any of these findings as this will greatly increase their potential as cancer therapeutics." (PMID 33005627, 2020). "In vitro reports in mouse embryonic stem cells and different cancer backgrounds where PARG has been silenced/depleted have consistently produced increased sensitivity to ionizing radiation (IR)." (PMID 33005627, 2020). "PARG is aberrantly overexpressed in most human cancers, suggesting that PARG is required for tumorigenesis and cancer survival." (PMID 32295316, 2020). "Accordingly, we observed significant increases in PARG expression with CRPC compared to primary cancer in the data sets GSE74367 and GSE70770 31,32." (PMID 32123273, 2020). "The therapeutic potential of targeting PARylation using PARP or PARG inhibitors alone or in combination with other therapies clearly has promise as an anti-cancer therapy." (PMID 33005627, 2020). "This article discusses what is known about the functions of PARP and PARG and the potential future implications of pharmacological inhibition in anti-cancer therapy." (PMID 33005627, 2020). "In support of this, survival studies of certain human cancer cell lines with PARG knockdown synergistically enhances the lethality to DNA-damaging agents such as alkylating agents and cisplatin." (PMID 32295316, 2020). "Here the authors provide structural and biological insight with small molecule PARG inhibitors and show that PARG inhibition sensitizes cells to ionizing radiation and kills cancer cells through replication fork defects." (PMID 31827085, 2019). "With these conflicting reports in mind, herein, we examined the TCGA database and found that in most human cancers PARG expression is upregulated, supporting the notion that PARG enzymatic function is required for tumorigenesis." (PMID 31827085, 2019). "With these points in mind, we hope that JA2131 will enable many studies evaluating the potential value of specifically inhibiting PARG in various cancer therapeutic strategies." (PMID 31827085, 2019). "Fueled by the success of PARP inhibition (PARPi) as a therapeutic strategy for the treatment of many cancers, the field is now exploring the therapeutic potential of PARG inhibition (PARGi)." (PMID 30862789, 2019).
cancer (continued). "This PARGi is selective, cell-permeable, prevents PAR removal by PARG, and kills cancer cells at a level similar to Olaparib." (PMID 31827085, 2019). "To identify suitable cell lines to test PARGi, we evaluated PARG protein expression patterns on a panel of prototypic cancer cell lines." (PMID 31827085, 2019). "We will conclude by discussing the therapeutic target potential of ADP-ribose erasers, focusing on the use of PARG inhibitors in synthetic lethal approaches against cancer." (PMID 30862789, 2019). "It was previously reported that genetic knockdown of PARG results in sensitization of cancer cells to chemotherapeutic agents and radiation, and tumor-specific killing in BRCA2-deficient cancer cells." (PMID 31827085, 2019). "This suggests that PARG and/or other de‐PARylating enzymes have sufficient capacity in cancer cells to warrant the timely degradation of PAR (Alvarez‐Gonzalez and Althaus, 1989)." (PMID 30289618, 2019). "This was the first study that reported evidences to support an oncogenic role of PARG in BaP induced carcinogenesis, which provided a new perspective for our understanding in BaP exposure induced cancer." (PMID 27003318, 2016). "The increased sensitivity of PARG-deficient cells to the anti-neoplastic agent HU that blocks replication supports the concept of PARG inhibition to potentialize cancer therapies relying on genotoxic drugs as previously proposed." (PMID 24906880, 2014). "Future studies involving the targeting of PARG in various types of cancer cells, as well as in vivo studies, will be required to further validate the chemotherapeutic value of targeting PARG." (PMID 23254695, 2013). "Experiments with PARG over-expression reveal an additional mechanism responsible for the widespread genomic hypomethylation in cancer cells." (PMID 19262751, 2009). "In conclusion, the genome methylation pattern following PARG over-expression mirrors the pattern characteristic of cancer cells, supporting our idea that the right balance between Parp/Parg activities maintains the DNA methylation patterns in normal cells." (PMID 19262751, 2009). "Tumors, which often exhibit heightened PARP activity, rely on timely PAR turnover, so cancers with replication stress or HR defects may be vulnerable to PARG inhibitors, as PAR accumulation at forks can precipitate fork collapse." (PMID 41190241, 2025). "PARG and NAMPT inhibitors could therefore represent therapeutic opportunities for cancers displaying PARP1 hyperactivity, including XRCC1-deficient cancers." (PMID 41459749, 2025). "In addition to PARP, PARG inhibition has also been explored for cancer treatment, following the resolution of the structure of the PARG catalytic site." (PMID 38360994, 2024). "And loss of PARG, induced olaparib resistance in BRCA1- or BRCA2-deleted cancer cells." (PMID 38625917, 2024). "Therefore, elucidation of the molecular mechanism of PARG in tumourigenesis should provide powerful theoretical support for the use of PARG inhibitors (PARGi) as cancer therapeutics." (PMID 39375922, 2024). "Targeting poly(ADP-ribose) glycohydrolase (PARG) is currently explored as a therapeutic approach to treat various cancer types, but we have a poor understanding of the specific genetic vulnerabilities that would make cancer cells susceptible to such a tailored therapy." (PMID 38360994, 2024). "Moreover, we showed that PARG is essential for cell survival, which can be exploited for cancer treatment." (PMID 38578205, 2024). "More surprising was the identification of eight hitherto unknown domains of the PARP and PARG families considering the past year’s intense scrutiny of PARPs in cancer therapy." (PMID 39237506, 2024). "Given that PARG accounts for more than 90% of dePARylation activity, selective PARG inhibitors are being developed as potential anti-cancer agents." (PMID 38578205, 2024). "Thus, PARGi can be potentially used to treat these PARPi-resistant cancers, especially those with low PARG expression." (PMID 38578205, 2024).
cancer (continued). "Thus, there is significant interest in further developing these PARG inhibitors for cancer treatment." (PMID 38578205, 2024). "In addition, we revealed that the PARG level is a potential biomarker for PARGi-based cancer therapy." (PMID 38578205, 2024). "However, this PARG inhibitor offers experimental and fundamental insights into its function of PARG and its significance as a cancer treatment molecular target." (PMID 36053937, 2023). "Targeting TARG1 in these PARPi-resistant cancer cells with PARG downregulation could thus be a promising therapeutic strategy, highlighting the need to develop TARG1 inhibitors." (PMID 37676774, 2023). "Therefore, we evaluated the effects of the PARP inhibitor olaparib, as an approved anti-cancer agent, and the PARG inhibitor PDD00017273 on osteoblast differentiation." (PMID 35563432, 2022). "Our data suggest that the upregulation of PARG may be potentially useful for the tumor growth inhibition in cancer treatment and as anti-inflammatory intervention." (PMID 35585513, 2022). "Moreover, when we utilize the TCGA PanCancer Atlas for relative mRNA expression in different tumors to corresponding normal tissue, the mean expression of PARG mRNA in ccRCC was the lowest and most severely down-regulated across all tested cancer types." (PMID 34638458, 2021). "Therefore, many natural ingredients have also been studied as PARP and PARG inhibitors, and investigation is underway for improved cancer therapeutics." (PMID 34638660, 2021). "First, we selected the down-regulated genes at PNX0010 under PARG overexpression that are related to cancer development: ID1, ID2, ID3, and SERPINE1 and performed qPCR analysis for 786-O, 769-P, SK-RC-45, and SK-RC-26b cell lines treated with the 10 uM PARP-1 inhibitor rucaparib for 24 h." (PMID 34638458, 2021). "When examined by CIBERSORT analysis through the TIMER2.0 web server, the mRNA levels of many DDR factors, such as RPA1, Ku70, Ku80, MRE11A, RAD50, NBS1, PRKDC, RAD51, PARG and XRCC4, were negatively associated with cytotoxic CD8+ T cells infiltration levels across various cancer types." (PMID 34970273, 2021). "The key question is whether PARG inhibitors will offer dissimilar therapeutic opportunities compared with PARP inhibitors in the treatment of cancer." (PMID 34778062, 2021). "Furthermore, PARG activity was recently demonstrated to play a critical role in telomere extension through the alternative lengthening of telomeres (ALT) mechanism in cancer cells, including U2OS." (PMID 34019811, 2021). "Furthermore, we reveal a synthetic lethal interaction between ARH3 and PARG and identify loss of ARH3 as a mechanism of PARP inhibitor resistance, both of which can be exploited in cancer therapy." (PMID 34019811, 2021). "Other cancer progression-related genes that became differently expressed in PNX0010 cells under PARG overexpression are serpin family E member 1 (SERPINE1), colony-stimulating factor 2 (CSF2 or GM-CSF), ubiquitin specific peptidase 10 (USP10), and growth differentiation factor 15 (GDF15)." (PMID 34638458, 2021). "The deletion or inhibition of eraser enzymes such as PARG may potentiate synthetic lethality drugs in cancers with mutant phenotypes." (PMID 34639169, 2021). "Thus, it indicates that ccRCC cells lost tumorigenicity under PARG overexpression and were unable to proliferate at surface-free state, the unique trait of cancer cells." (PMID 34638458, 2021). "Inhibitors of PARP and poly(ADP-ribose) glycohydrolase (PARG) are used in cancer therapy." (PMID 34526971, 2021). "Indeed, the PARG inhibitor gallotannin synergized with the CHK1 inhibitor UCN-01 to sensitize cancer cells to IR." (PMID 34197606, 2021). "Given the high rate of HR defects in OC, we hypothesize that inhibiting PARG may be an effective alternative therapeutic strategy for targeting specific OC cancer cells that are dependent on this activity." (PMID 34778062, 2021).
cancer (continued). "Moreover, we identify the synthetic lethal interaction between ARH3 and PARG, which is caused by extreme levels of PARylation, and highlight ARH3 as a promising drug target and a biomarker for cancer cell sensitivity to PARP and PARG inhibition." (PMID 34019811, 2021). "Moreover, PARG downregulation was reported as one of the mechanisms of PARPi resistance due to the resultant increase in PARylation, and PARG was identified as a top PARPi resistance gene in cancer cells." (PMID 34019811, 2021). "Recently, PARG has also emerged as a promising drug target in cancer." (PMID 33674744, 2021). "In general, cancers with high levels of replication stress and genomic instability due to DNA repair deficiency and/or oncogene-induced increase in replication origin firing are particularly responsive to PARP and PARG inhibition." (PMID 32029455, 2020). "The accumulated evidence thus led us to hypothesize that PARG may impact both cancer development and cancer therapy." (PMID 32344695, 2020). "Therefore, inducing cell death via PARG inhibition and manipulation of the PAR cycle through PARP1/PARG inhibition is an attractive target for cancer therapy." (PMID 32295316, 2020). "Inhibitors of poly(ADP-ribose) glycohydrolase (PARG) exploit and exacerbate replication deficiencies of cancer cells and may complement PARP inhibitors in targeting a broad range of cancer types with different sources of genomic instability." (PMID 32029455, 2020). "This novel regulatory mechanism involving TLR9 in the posttranscriptional modification of PARP1 and the level of PARG may contribute to the development of a cancer therapy involving the PARP or PARG signaling pathway." (PMID 32483468, 2020). "PARG genetic knockdown sensitizes various cancer cells to chemotherapeutic agents and radiation and may cause tumor-specific killing in BRCA2-deficient cancer cells." (PMID 31827085, 2019). "Poly(ADP-ribose)ylation (PARylation) by PAR polymerase 1 (PARP1) and PARylation removal by poly(ADP-ribose) glycohydrolase (PARG) critically regulate DNA damage responses; yet, conflicting reports obscure PARG biology and its impact on cancer cell resistance to PARP1 inhibitors." (PMID 31827085, 2019). "Here, we found that PARG expression is upregulated in many cancers." (PMID 31827085, 2019). "We sought to test PARG inhibition in cancer cells and found that although existing PARG inhibitors (PARGi) have proven valuable, issues with potency, bioavailability, rapid clearance, selectivity, or defined mechanism of action can cloud their applications for biology." (PMID 31827085, 2019). "Indeed, the general importance of PARG in cancer progression is underscored by finding that catalytically active PARG leads to poor prognosis and survival, while expression of enzymatically-defective protein played no part in tumor growth." (PMID 31827085, 2019). "Thus, our collective cytotoxicity data show that JA2131 indeed acts through inhibition of PARG and that it selectively kills cancer cells." (PMID 31827085, 2019). "Our TCGA database analysis revealed that in most human cancers PARG expression is upregulated." (PMID 31827085, 2019). "Increased hydrolysis of PARylation chains facilitates cancer growth through enhancing estrogen receptor (ER)-driven proliferation, but oncogenic transformation has not been linked to increased PARG expression." (PMID 30459355, 2019). "Moreover, our PARG inhibitor sensitizes cells to radiation-induced DNA damage, suppresses replication fork progression and impedes cancer cell survival." (PMID 31827085, 2019). "The reported chemosensitizing effects are variable, but gene depletion or silencing of PARG using siRNA has consistently resulted in sensitivity to ionising radiation (IR) in mouse ES cells and human cancer cell lines, with accumulation of mitotic defects and death occurring by mitotic catastrophe." (PMID 29179156, 2018).
cancer (continued). "The results provided a novel insight into the possibility of targeting PARG in BaP induced cancer." (PMID 27003318, 2016). "Since no PARG inhibitors are available for in vivo studies, PARG was depleted by siRNA in several cancer cell lines, proficient or deficient for BRCA1 and/or PTEN." (PMID 27375368, 2016). "Since PARG silencing blocks basic TGFβ signaling responses, development of specific PARG inhibitors may provide a potential tool that could simultaneously modulate PARG and TGFβ activity during various diseases such as cancer." (PMID 25133494, 2014). "PARG mRNA levels are only significantly higher in two cancer cell lines." (PMID 25139788, 2014). "Markedly, in accordance with the development of PARG inhibitors, the use of the PARG-siRNA may contribute to a treatment of cancer with a reduced dose of anti-cancer drugs or ionizing radiation." (PMID 23467693, 2013). "However, we do provide further insight into the feasibility of targeting PARG in cancer and the ability of utilizing our PARG-null cell model to evaluate the ability of future PARP inhibitors to inhibit PAR synthesis." (PMID 23254695, 2013). "Because hnRNP PARylation inhibited the RNA-binding activity of hnRNP A1, PARG inhibitors may have therapeutic benefit for patients with hnRNP A1-dependent tumors by interfering with the metabolism of cancer cells." (PMID 23921685, 2013). "Thus, targeting PARP-1 and PARG are strategies to inhibit their genome-protecting effects in cancer cells and thereby induce cancer cell death." (PMID 23254695, 2013). "Therefore, the targeting of PARG appears to be a feasible strategy to improve the chemotherapeutic treatment of cancer patients in the future." (PMID 23254695, 2013). "Thus, the knockdown or genetic disruption of PARG is known to have a deleterious effect on cancer cells." (PMID 22839996, 2012). "It was also hoped that a global view of the PARP-1, PARP-2 and PARG interactomes may help to grasp the ramifications of cancer treatment by PARP inhibitors, either in terms of therapeutic efficiency or side effects." (PMID 20388209, 2010). "PARGi may be a promising strategy for the treatment of these cancers with low PARG expression." (PMID 38578205, 2024). "However, TYMS, DUT, POLB, LIG1 and FEN1 have been identified by others as PARGi synthetic lethality genes, and these observations support the notion that inhibition of nucleotide biosynthesis and BER can sensitize cancer cells to pharmacological PARG inhibition." (PMID 39015544, 2024). "Moreover, in PARP inhibitor-resistant cancers, PARG inhibitors may impair cancer cell survival by suppressing replication fork progression and show comparable killing ability." (PMID 36900418, 2023). "Therefore, our results are supported by available data that PARG level upregulation could be benefited for several types of cancer." (PMID 35585513, 2022). "In conclusion, based on the results of this work, we suggest that, although the crosstalk between PARP and PARG in tumorigenesis is not yet fully understood, upregulation of PARG’s activity may be a potentially useful and unexplored avenue in the development of cancer treatment." (PMID 35585513, 2022). "However, despite a great interest in PARP1 as a target for cancer therapy and the arising therapeutic potential of PARG inhibition, the relative contribution of ARH3 and PARG in regulating the levels of ADPr in human cells remains unclear." (PMID 34019811, 2021). "Thus, according to our data, PARPi-resistant cancers with PARG downregulation could be targeted by ARH3 inhibitors, further highlighting the need for ARH3 inhibitor development." (PMID 34019811, 2021). "Given that PARPs’ or PARG activities have been demonstrated to interfere with nucleocytoplasmic shuttling of FUS in the cytoplasm upon genotoxic stress, these data may extend the range of applications of PARPs or PARG inhibitors from cancer to neurodegenerative diseases." (PMID 32987654, 2020).